NR4A3 (nuclear receptor subfamily 4 group A member 3)
Diseases named in the same sentence as NR4A3 in open-access papers (continued):
Sharing a sentence is not in itself a finding about the gene and the disease.
tumor (continued). "Myeloid cells and T cells were the most abundant cell types in tumors and normal lung tissues, while tumor-associated macrophage-folate receptor 2 (TAM-FOLR2) and CD4+ nuclear receptor subfamily 4 group A member 3 (NR4A3) exhibited sharp increases in invasive adenocarcinoma (IA)." (PMID 37532692, 2023). "The differences in activities are probably due to tissue-specific regulation of different sets of target genes in different tumor types, suggesting that NR4A3 protein likely interacts with tissue-specific cofactors that help regulate its specificity and activity." (PMID 32867110, 2020). "Interestingly, Nr4a3 knockdown increased BrdU incorporation, tumor weight and decreased TUNEL positive cells in BRE-AS1 expressing H1299 cells." (PMID 31683815, 2019). "Interestingly, our results have shown that mRNA levels of both Nr4a1 and Nr4a3 were increased in spleen during the early stage of tumor progression and were decreased during advanced stages." (PMID 30037009, 2018). "Overexpression of NR4A3 suppressed tumor growth in vitro and in vivo, strongly suggesting that it may be a novel tumor suppressor in GC, as increased NR4A3 hypermethylation associated with shorter overall survival." (PMID 27528092, 2016). "In this regard, the shorter overall survival we observed in patients with NR4A3 methylation may likely be due to chemo-resistance-related tumor recurrence." (PMID 27528092, 2016). "Moreover, GC patients with higher methylation or lower expression of NR4A3 demonstrated significantly shorter overall survival, indicating a potential tumor suppressor role." (PMID 27528092, 2016). "NR4A3 has previously been demonstrated to be a critical tumor suppressor of myeloid leukemogenesis and possesses two 3'UTR seed matches to miR-10a, which may increases capacity for translational repression." (PMID 22348345, 2012). "In studies on tumor-inoculated mice, it was shown that CAR-T cells deficient in both TOX and TOX2, or with triple KO of NR4A1, NR4A2, and NR4A3, had a greater anti-cancer activity and improved animal survival; therefore, targeting the TOX/NR4A axis may reduce the depletion of CAR-T cells in TME." (PMID 37296906, 2023). "Interestingly, in comparison to wild-type CAR T cells, the transfer of NR4A1, NR4A2, and NR4A3 triple knockout CAR T cells to tumor-bearing mice decreased the proportion of highly exhausted CAR T cells among the tumor-infiltrating lymphocytes and led to a better prognosis." (PMID 35606821, 2022). "Whether NR4A3 is a bona fide tumor suppressor needs further elucidation." (PMID 33634114, 2021). "However, there are not yet any studies describing whether these or other compounds may be able to mitigate the transcriptional or oncogenic activities of NR4A3 or NR4A2 in tumor cells." (PMID 32867110, 2020). "mRNA from the tumour samples ID1 and ID2 were used for expression analysis in our previous study and both samples had upregulated expression of STX17 and NR4A3 consistent with our interpretation that the copy number expansion detected in the present study may be relevant for tumour development." (PMID 22857264, 2012). "In vivo results also confirmed that NR4A3 overexpression elevated Bip and CHOP expression in tumor tissues." (PMID 40762284, 2025). "The tumour cells in ACiCas are very sensitive to markers like DOG-1, EMA, SOX10, and NR4A3, a novel specific marker, and are stained well." (PMID 41328110, 2025). "The first tumor-reactive subcluster, resident memory T cells (TRM), was characterized by specific expression of NR4A2, NR4A3, and TUBA4A, undertaking immune surveillance and immune activation." (PMID 40315321, 2025). "The results of our in vitro and in vivo studies showed that NR4A3 overexpression inhibited HCC cell proliferation, tumor formation and promote DNA damage." (PMID 39664575, 2024). "The protein levels of NR4A3 and CDKN2AIP in mouse tumor tissues were examined by Western blot analyses." (PMID 39664575, 2024).
tumor (continued). "The expression of NR4A3 was negatively correlated with Ki67 and PCNA in TCGA dataset as well as in NR4A3-overexpressing tissues collected from nude mice with tumor xenografts." (PMID 39664575, 2024). "A pioneering research indicates that NR4A3 inhibition significantly promotes epithelial-mesenchymal transition (EMT), proliferation, migration and invasion in tumor cells." (PMID 35768408, 2022). "The expression level of IL37 in the tumor was significantly higher than that in the normal tissues, while SLC5A5, NR4A3, and ODF3L1 were highly expressed in normal tissues than those in tumors." (PMID 34248843, 2021). "Both NR4A1 and NR4A3 are silenced in AML and display tumor-suppressing qualities suppressing MYC activity." (PMID 33634114, 2021). "Among these genes, SERPINE2 was expressed at high levels both in AcCC tumor samples and NCI-H292 cells after overexpression of both NR4A3 and Myb." (PMID 32867110, 2020). "We have previously shown that the AML tumor suppressors, NR4A1 and NR4A3 function redundantly in Kasumi-1 AML-ETO positive human AML cells to inhibit AML cell growth and reprogram a subset of AML gene expression signatures." (PMID 26938745, 2016). "In conclusion, our findings provide initial evidence suggesting that NR4A3 suppresses HCC cell proliferation by regulating levels of CDKN2AIP expression, thereby playing a pivotal role as a tumor suppressor during HCC progression both in vitro and in vivo settings." (PMID 39664575, 2024). "Of the 191 pairs, 100 (52.36%) had lower NR4A3 protein expression in tumor liver tissues than in noncancerous tissues, 61 (31.94%) had similar levels, and only 30 (15.71%) had higher NR4A3 protein expression." (PMID 39664575, 2024). "In contrast, the TF motifs (e.g., NR4A1, NR4A2, and NR4A3) orchestrating T-cell exhaustion were exclusively enriched in tumor-specific Tex cells but not in plaque-specific Tem cells." (PMID 38491170, 2024). "Splenocytes were cultured with TCM (representing the TME) from infected or non-infected tumour organoids and T cells were polyclonally activated for 4 or 16 h, representing early and late timepoints for activation and Nr4a3 expression." (PMID 39558103, 2024). "Tumours from PBS and Salmonella-treated mice were subjected to α-CD3 and α-CD28 stimulation ex vivo, and Nr4a3-Timer was measured in T cells, with the hypothesis of dysfunctional activation." (PMID 39558103, 2024). "Overexpression of NR4A3 inhibited HCC cell proliferation, cell cycle progression, clone formation and promoted DNA damage while subcutaneous neoplasia experiments showed that it suppressed tumor formation whereas knockout or knockdown promoted it." (PMID 39664575, 2024). "Knockout of PRDM1 and NR4A3 improved the anti-tumor response by increasing the generation of long-lived memory cells, counteracting exhaustion in tumor-infiltrating CAR T cells, and enhancing the overall anti-tumor response." (PMID 38693513, 2024). "Nuclear receptor subfamily 4 group a member 3 (NR4A3, also known as NOR1) belongs to the orphan nuclear hormone receptor superfamily, which is a nuclear receptor and a transcription factor involved in various cell metabolism and tumor suppression processes." (PMID 37905340, 2023). "Dual knockout of PRDM1 and NR4A3 skewed CAR T cell phenotypes away from TIM-3+CD8+ and toward TCF1+CD8+ to counter exhaustion of tumor-infiltrating CAR T cells and improve antitumor responses, effects that were not achieved with PRDM1 and NR4A3 single knockout alone." (PMID 36350986, 2022). "Similar to the results obtained from the PC3-PSMA model, NR4A3 single KO CD19 CAR T-cells failed to suppress tumor growth." (PMID 36350986, 2022). "However, when PRDM1 KO was combined with NR4A3 KO, CAR T-cells induced rapid tumor clearance and durable antitumor efficacy." (PMID 36350986, 2022).
tumor (continued). "Whereas AAVS1, PRDM1, and NR4A3 single KO CAR T-cells controlled tumor growth in about 50% of mice in the high-burden PC3-PSMA cell xenograft model, PRDM1/NR4A3 double KO CAR T-cells successfully suppressed tumor growth in all treated mice, in association with overall prolongation of survival." (PMID 36350986, 2022). "Indeed, the Nr4a triple-knockout (Nr4a1, Nr4a2 and Nr4a3) in CAR TILs promoted tumor regression and prolonged the survival of tumor-bearing mice." (PMID 34639168, 2021). "In particular, compared to the EWSR1-NR4A3 EMC subtype, TAF15-NR4A3 EMC over-expresses pro-tumorigenic axonal guidance molecules, supporting the notion that the type of NR4A3 partner dictates an axon guidance switch that affects tumor biology." (PMID 32967265, 2020). "NR4A1/NR4A3 silencing in AML is mediated through the blockade of transcription elongation, while treatment with dihydroergotamine (DHE) rescued NR4A silencing and allowed their tumor-suppressing ability to reactivate with concomitant slowing of AML progression in vivo." (PMID 33634114, 2021). "In addition, we also discovered one tumor sample with a highly homologous gene, NR4A2, chromosomal translocation to the enhancer region on chromosome 4, suggesting possible redundant functions of NR4A2 for NR4A3." (PMID 32867110, 2020). "Although the vast majority of parotid AcCCs do express NR4A3 by immunohistochemistry, the lack of NR4A3 mRNA expression in our case does not directly argue against the diagnosis, as little is known regarding the NR4A3 gene status in non-parotid manifestations of this tumor type." (PMID 32519264, 2021). "Next-generation sequencing (NGS) analysis revealed copy number loss of SMARCB1 and a novel GSTT1::IGLC7 fusion in the tumor, while no other gene rearrangements, including those involving EWSR1, NR4A3, or FUS, were detected." (PMID 42052495, 2026). "On addition of xevinapant to CRT, the numbers of tumor-infiltrating cytotoxic CD8+ T cells and NK cells were reduced, with remaining CD8+ T cells characterized by PD-1hi CD38hi expression and Nr4a3 dynamics consistent with nonresponsiveness to antigenic restimulation." (PMID 41123992, 2025).
cancer (45 papers, 2010 to 2025). A tumor composed of atypical neoplastic, often pleomorphic cells that invade other tissues. "NR4A3 has also been implicated in the regulation of proliferation, apoptosis, and cell cycle arrest in cancer cells and plays a major role in the apoptotic responses of epithelial cancer cells, including their sensitivity to antineoplastic agents." (PMID 38943627, 2024). "Specifically, cancer-associated genes, including VEGF-A, NR4A3, Ki-67, and EpCAM, were significantly down-regulated." (PMID 40359186, 2025). "In this phase IIA clinical study, upregulated expression of cancer-associated genes, including those linked to tumorigenesis and metastasis, such as VEGF-A, NR4A3, MKi67, and EpCAM were detected as early as Day 1 in the iCCA patients (Groups 1, 2, and 3)." (PMID 40359186, 2025). "For the overall group analysis, patients in Groups 1 and 2 displayed similar expression patterns, particularly the downregulation of cancer-associated genes (Fas, NOS2, VEGF-A, NR4A3, MKi67, and EpCAM), as well as the pro-inflammatory cytokine IL-6." (PMID 40359186, 2025). "MiR-665 promotes cancer growth, invasion, and metastasis by targeting NR4A3, thus activating the RAF/MEK/ERK pathway." (PMID 37894282, 2023). "Little is known about the functions of NR4A3 in cancer, though some crucial findings have been reported." (PMID 33328994, 2020). "Altogether, we proved that CD51-ICD interacted with NR4A3 to promote PNI in cancer cells, which might be explained by the coactivator effect of CD51-ICD on transcription regulation." (PMID 37174090, 2023). "Furthermore, we assessed the phenotype of NR4A3 affecting the neurotropism on cancer cell neurotropism at the cellular level." (PMID 37174090, 2023). "Both the co-culture migration assay and the time-lapse cell motility assay showed that overexpression of NR4A3 alone suppressed the neurotropism of cancer cells toward RSC96 cells, while cells transfected with the CD51-ICD vector exhibited the opposite phenomenon." (PMID 37174090, 2023). "Furthermore, some other studies recently demonstrated NR4A3 to be involved in promoting apoptosis by inducing expression of pro‐apoptotic genes in cancer cells, while chondrocyte apoptosis is a valid target to modulate cartilage degeneration." (PMID 31701670, 2020). "As reported, NR4A3 regulates the transcription of overlapping target genes and may serve as a balance regulator of proliferation, apoptosis, and differentiation, garnering significant attention in cancer research." (PMID 39474111, 2024). "This signaling pathway includes the up‐regulated transcription factors NR4A3 and EGR1/3, which are known regulators of cancer progression, EMT, angiogenesis, and inflammation." (PMID 39739693, 2025). "The NR4A family (NR4A1/NUR77, NR4A2/NURR1, and NR4A3/NOR1) regulates mitochondrial function, energy metabolism, and inflammation, with implications in CVD, neurodegeneration, and cancer." (PMID 40926269, 2025). "The NR4A proteins, including NR4A3, can regulate Treg development through the activation of FOXP3 and have therapeutic potential in immune disorders and cancer." (PMID 37532692, 2023). "The activation of genes such as NR4A3, MET, ZEB1, CSF1, CSF2, CSF3, which can be involved in transcriptional dysregulation in cancer or hematopoietic cell lineage signaling pathways, can also be involved in cell differentiation." (PMID 37606991, 2023). "Seven winning TFs (ETV4, ID2, MEIS1, NR4A3, RARA, TCF3, and ZBTB16) are related to transcriptional misregulation in cancer (p-value: 6.9 × 10−5)." (PMID 36101460, 2022). "Given that NFAT in the absence of AP-1 induces a chronic T cell exhaustion phenotype, Nr4a3-Tocky will be useful tools for understanding NFAT pathway activity in models of T cell dysfunction and cancer." (PMID 33147449, 2020).
cancer (continued). "Considering that gene function varies across different cancers due to tissue heterogeneity and cellular contexts, we examined mRNA and protein expression levels of NR4A3 between HCC and adjacent noncancerous tissues." (PMID 39664575, 2024). "NR4A3 mRNA expression was lower in all cancer subtypes compared to Normal-like subtypes with no meaningful differential expression between cancerous subtypes." (PMID 35547878, 2022). "Intriguingly, evidence of NR crosstalk was found between NR class IV genes (NR4A1, NR4A2, NR4A3) in 20/21 cancer types (absent in SKCM)." (PMID 32024906, 2020). "In addition, the anti-metabolite cancer drug, 6-mercaptopurine used to treat leukemia, could induce NR4A2 and NR4A3 through binding to AF-1 domain at the N-terminal of the latter; however, how it induced NR4A2 remains to be further researched." (PMID 33328994, 2020). "A uniquely enriched pathway of all five PCGs (FSTL3, KLF6, MLF1, NR4A3, and SDC4) was “Transcriptional misregulation in cancer” (P = 0.048), suggesting that those five PCGs and their regulating lncRNAs may play roles in transcriptional regulation levels in THCA." (PMID 29340074, 2017). "Furthermore, pairwise Pearson correlation for 21/33 cancer types revealed recurrent correlation between the expression patterns for multiple class I-III NRs and retinoid X receptors (RXRs), as well as, strong positive correlation between class IV NRs (NR4A1, NR4A2, NR4A3) in 20/21 pan-cancers." (PMID 32024906, 2020). "Genes located above TRIM46 in the heatmap, such as ALOXE3, NR4A3, and TMEM88, did not exhibit similar upregulation in advanced-stage cancer tissues." (PMID 39937005, 2025). "It was demonstrated that the NR4A family has a role in T cell development from thymic differentiation to peripheral response against infections and cancer; the overexpression of NR4A1 and NR4A3, but not NR4A2, induces thymocyte apoptosis in vivo." (PMID 35407632, 2022).
infection (11 papers, 2018 to 2026). The state of being infected such as from the introduction of a foreign agent such as serum, vaccine, antigenic substance or organism. "Infection elicits an inflammatory response and dysregulates genes associated with the innate immune system (CCL20, CD38, LCN2 and NR4A3)." (PMID 39666439, 2025). "Only 5 cellular genes (Cyp1a1, Ltf, Nr4a3, Per2 and Zbtb16) were significantly modulated on day 1 post-infection." (PMID 35812400, 2022). "In the orphan NR family, all three members of Nurr family (Nr4a1, Nr4a2 and Nr4a3) exhibited repression while Rora was upregulated during later stages of infection." (PMID 29396519, 2018). "Consistent with our in vitro findings, we observed decreased expression of Nr4a3 at 12 and 48 h post infection and increased expression of Rora at 48 h post infection." (PMID 29396519, 2018). "Immunofluorescence analysis of NR4A3 was used to confirm effective infection in the joints." (PMID 31701670, 2020). "As NR4A3 is expressed very early following T cell activation, we performed these analyses at relatively early time points (12h after in vitro stimulation for ATAC-seq and in vivo day 3 post-infection for RNA-seq)." (PMID 33597928, 2020).
cardiovascular disease (4 papers, 2017 to 2023). "There are 20 unique genes within the 9q22.33 locus and three genes (TGFBR1, NR4A3, and INVS) were linked to cardiovascular diseases." (PMID 28710368, 2017). "NR4A3 belongs to the steroid‐thyroid hormone retinoid receptor superfamily and function as critical transcriptional regulators of inflammation, differentiation, proliferation and apoptosis in cardiovascular diseases." (PMID 33942991, 2021).
hematologic neoplasms (3 papers, 2019 to 2025). "Reduced expression and hyper-methylation of NR4A1 and NR4A3 are commonly encountered phenomenon in blood cancers." (PMID 40028473, 2025).
adenocarcinoma (1 paper, 2021). A common cancer characterized by the presence of malignant glandular cells. "One adenocarcinoma of the parotid gland showed a solid pattern without mucous secretion, and IHC was positive for S100, SOX10, and DOG1 and negative for NR4A3." (PMID 34036223, 2021).
bacterial infection (1 paper, 2018). "The PBMCs obtained from TB patients also showed significant changes in the expression of Nr4a3 and Rora pointing towards their plausible role in bacterial infection." (PMID 29396519, 2018).
hematological malignancies (1 paper, 2024). "In recent years, studies have revealed the significant involvement of NR4A3 in tumorigenesis, particularly in hematological malignancies." (PMID 39664575, 2024).
NR4A3 also shares sentences with these, for which no sentence is quoted: cardiac hypertrophy (4 papers); salivary gland acinic cell carcinoma (4); metabolic disease (3); soft tissue sarcoma (3); Coronary artery disease (2); epilepsy (2); Glucose intolerance (2); hepatocellular carcinoma (2); Hyperglycemia (2); immune disorders (2); myxoid liposarcoma (2); solitary fibrous tumor (2); acute kidney injury (1); acute myocardial infarction (1); acute promyelocytic leukemia (1); adenoid cystic carcinoma (1); adrenal hypoplasia (1); allergic asthma (1); alveolar soft part sarcoma (1); aneurysm (1); angiosarcoma (1); calcification (1); chondroma (1); chronic lymphocytic leukaemia (1); COVID-19 (1); dementia (1); dermatofibrosarcoma protuberans (1); epithelioid hemangioendothelioma (1); epithelioid sarcoma (1); fatty liver disease (1).
A further 28 diseases each share a sentence with NR4A3 in 1 paper.